FGFR1 (fibroblast growth factor receptor 1)
Diseases named in the same sentence as FGFR1 in open-access papers (continued):
Sharing a sentence is not in itself a finding about the gene and the disease.
melanoma (continued). "Our results show that Ust and 2-O sulfation levels of CS/DS affect the synthesis of Itga5 and FgfR1 and, in addition, the function of α5β1 integrin which leads to impaired melanoma cell adhesion." (PMID 28107390, 2017). "In line with this, we have previously shown that combined inhibition of BRAF and FGFR1 has synergistic anti-melanoma effects." (PMID 29152117, 2017). "FGF-FGFR -based autocrine signaling was also suggested by overexpression of FGF2, FGF5 and FGF8 and different isoforms of the FGF receptors (FGFR1-4) in melanoma cells." (PMID 27102439, 2016). "IGF-1R is expressed by all the melanoma cell lines and FGFR1 is highly expressed in 7 out of the 9 analyzed melanoma cell lines." (PMID 27102439, 2016). "IMB-R1 staining was significantly stronger in cancer cells in the breast, lung, lymphoma, esophagus, bladder and ovary tissues as well as in melanoma cells compared to adjacent normal tissue, suggesting FGFR1 expression is increased in these tumors." (PMID 26201468, 2015). "Antisense-mediated inhibition of FGF2 or FGFR1 led to growth regression of xenografts formed by human melanoma cells." (PMID 26056081, 2015). "For example, there is evidence that melanoma is driven in part by bFGF acting on FGFR-1 on tumor cells." (PMID 21781317, 2011). "Melanomas express basic fibroblast growth factor (bFGF) and fibroblast growth factor receptor-1 (FGFR-1) in their dermal nevocytes and in the stroma." (PMID 15324457, 2004). "The role of both FGF2 and FGFR1 signalling is suggested in melanoma progression." (PMID 38473753, 2024). "The data showed that combination of FGFR1-LDHA inhibitors could further suppress the glycolysis of melanoma cells in CCHE1-depleted cells." (PMID 37480145, 2023). "Additionally, the proliferation of melanoma cells that were co-treated with inhibitor of FGFR1 PD166866 and LDHA inhibitor GSK2837808A was detected by CCK-8 assay." (PMID 37480145, 2023). "FGFR1 is exceptional as it is expressed in the majority of melanomas at a high level." (PMID 31167513, 2019). "Early studies indicated that FGF2/FGFR1 might be of importance for autocrine growth control and melanoma progression." (PMID 31167513, 2019). "It has been shown that the FGF2/FGFR1 signaling is also crucial for melanoma angiogenesis as FGF2 secretion by melanoma cells could induce the mitogenic effects on endothelial cells and fibroblasts." (PMID 31167513, 2019). "Enhanced NFAT activity in FGF5 overexpressing cells could be a consequence of FGFR1-mediated PLCγ activation as previously reported and could contribute to enhanced melanoma growth via an anti-apoptotic activity." (PMID 29152117, 2017). "Human melanoma commonly expresses high levels of FGFR1 and FGF2." (PMID 26056081, 2015). "Taken together, our data suggested that FA could function as a novel potent FGFR1 inhibitor that suppresses tumor angiogenesis and melanoma growth." (PMID 26473837, 2015). "In melanoma there is evidence for a bFGF/FGFR-1 autocrine loop driving proliferation in vivo indicating that in some tumor types inhibitors such as E7080 may also have direct effects on the proliferation of tumor cells." (PMID 21781317, 2011). "It has been demonstrated that melanoma cells cannot survive if bFGF or FGFR1 are targeted." (PMID 16721364, 2006). "Antisense targeting of bFGF/FGFR-1 in malignant melanomas blocks intratumoral angioneogenesis." (PMID 15324457, 2004). "One of the best characterised activators for cell growth, proliferation, differentiation and migration in melanoma is basic fibroblast growth factor (bFGF), a multifunctional cytokine that interacts with four different types of high-affinity receptors (FGFR1-4)." (PMID 16721364, 2006). "Most notably, 1,25(OH)2D3 sensitised A375 melanoma cells to the novel FGFRs inhibitor, CPL304110, at the posttranscriptional level, decreasing the FGFR1 and 2 protein level as well as their activation." (PMID 38473753, 2024).
melanoma (continued). "Significantly reduced cell proliferation was observed with the co-inhibition of FGFR1 and LDHA in CCHE1-depleted melanoma cells." (PMID 37480145, 2023). "In the study, we found that CCHE1 acted as a scaffold to facilitate the binding between FGFR1 and LDHA, which enhanced LDHA activity and glycolysis of melanoma cells." (PMID 37480145, 2023). "Significantly reduced melanoma cell proliferation and glycolysis were observed with co-inhibition of FGFR1 and LDHA in CCHE1-depleted cells, suggesting the key function of CCHE1/FGFR1/LDHA regulatory axis in melanoma." (PMID 37480145, 2023). "As a direct binding partner of FGFR1, CCHE1 was a novel regulator of glycolysis and also shed light on a new avenue for disrupting melanoma cell growth." (PMID 37480145, 2023). "Among melanoma patients treated with the anti-PD-1 drug pembrolizumab (GSE78220) 24, relatively higher FGFR1 mRNA expression was found in pre-treatment tumors from non-responding cases compared with that from responders." (PMID 35832090, 2022). "FGFR1 and to some extent FGFR4 are exceptional in contrast to FGFR2-3, and these receptors are expressed in the majority of melanomas." (PMID 31167513, 2019). "In 2/3 of melanomas, FGF2 was also expressed by keratinocytes in the epidermis, and FGFR1 was commonly detected in the epidermis." (PMID 31167513, 2019). "We investigate gene dosage effects of Vegfr2, Fgfr1, and Fgfr2 in three independent mouse models of tumorigenesis: two-stage skin chemical carcinogenesis, and sub-cutaneous transplantation of B16F0 melanoma and Lewis Lung Carcinoma (LLC)." (PMID 30283071, 2018). "FGFR1, the predominant receptor for FGF5, is abundantly expressed in melanoma cells and likely is responsible for transducing autocrine stimulation by FGF5." (PMID 29152117, 2017). "A study indicated that FA exerted antiangiogenesis activities at a nontoxic dosage via specifically targeting fibroblast growth factor receptor 1 (FGFR1) and its PI3K/Akt signaling pathway in melanoma." (PMID 27042656, 2016). "Taken together, our results indicate that ferulic acid targets the FGFR1-mediated PI3K-Akt signaling pathway, leading to the suppression of melanoma growth and angiogenesis." (PMID 26473837, 2015). "FGFR inhibition is highly relevant to melanoma, where autocrine stimulation via FGF2/FGFR1 constitutes a pivotal role in proliferation and survival." (PMID 21494657, 2011). "To establish the concentration of E7080 required to inhibit activation and downstream signaling from FGFR-1 and PDGFR-β we chose two cell lines which expressed both receptors: DX3 melanoma and U2OS osteosarcoma." (PMID 21781317, 2011). "No significant influence on the mRNA level of FGFR1 in RPMI7951 melanoma cells was observed under the listed experimental conditions." (PMID 38473753, 2024). "Among all cell lines tested in this study, FGFR1 was highly expressed in EGFR + NSCLC NCI-H1650, HCC827, NCI-H1975, and HER2 + BC HCC1569 cells and BRAF+melanoma RPMI-7951, IGR-39, and SK-MEL-3 cells, and FGF2 was highly expressed in NCI-H1650, HCC827, HCC1569, RPMI-7951, and IGR-39 cells." (PMID 37880373, 2023). "FGFR1 was detected in 86%, whereas FGF2 in 45% of primary melanomas." (PMID 31167513, 2019). "Analysis of VEGFR1, VEGFR2, FGFR1, FGFR3 and VE-Cadherin expression levels in B16F0 melanoma cells, and tumors isolated from control and DCKO mice showed ~30% reduced levels of VEGFR2 (but not VEGFR1) in DCKO mice compared to DFF control littermates, consistent with Vegfr2 haploinsufficiency." (PMID 30283071, 2018). "Because IGF-1R, FGFR1, and EGFR have been shown to play major roles in melanoma progression through autocrine signaling, and EGF-R, PDGFRβ, and IGF-1R have been implicated in resistance mechanisms to BRAF V600E targeted therapies, we were interested in validating these results." (PMID 27102439, 2016). "We did not detect changes in the expression of FGFR1 in any of the RUNX2-knocked down melanoma cell lines (data not shown)." (PMID 27102439, 2016).
melanoma (continued). "Activating KIT mutations have been identified in some melanoma subtypes (mucosal, acral and non-sun-exposed), and FGF receptor (FGFR)-1 mutations have been sporadically found in melanoma." (PMID 24920406, 2014). "Indeed, increased expression of heparan sulphate and fibroblast growth factor receptor 1, the receptor and co-receptor for AAV2, has been demonstrated in several melanoma cell lines, supporting the observation of increased transduction of melanoma cell lines by rAAV2." (PMID 23646140, 2013). "Melanoma cells could not survive in vitro and in vivo if FGFR1 or FG2F were targeted." (PMID 31167513, 2019). "Similarly, Fgfr1 levels were 4.5-fold up-regulated in pigmented versus non-pigmented mouse melanocytes (Student’s t-test P = 1.32 x 10−2), and 111.6-fold up-regulated in pigmented mouse melanoma cells, relative to non-pigmented such cells (Student’s t-test P = 1.47 x 10−2)." (PMID 33983985, 2021). "Reduced levels of the receptor tyrosine kinases IGF-1R, FGFR1, PDGFRβ, and EGFR were detected in the RUNX2 knocked down 1205LU melanoma cells as compared with the non-silencing (control) ShRNA-expressing 1205LU cells." (PMID 27102439, 2016). "In summary, our study indicated that FA exerted anti-angiogenesis activities at a non-toxic dosage via specifically targeting FGFR1 and its PI3K/Akt signaling pathway in melanoma." (PMID 26473837, 2015).
pancreatic cancer (42 papers, 2010 to 2024). "In the present study, FGFR1 is significantly associated with overall survival and disease-free survival in periampullary/pancreatic cancer patients." (PMID 32171280, 2020). "In contrast, Kornmann and colleagues reported that 57% (4/7) of pancreatic cancer cases showed immunoreactivity for the IIIc splice variant of FGFR1 (FGFR1 IIIc)." (PMID 30593273, 2018). "Of note, in our previous studies we observed that the overexpression of FGFR1 in pancreatic cancer was linked to a low-grade tumor and the better survival of patients, suggesting that it may serve as a good prognostic marker." (PMID 35683481, 2022). "High expression of FGFR1 might cause a severe desmoplastic reaction (increased fibrosis) and could be protective or antitumorigenic in pancreatic cancers." (PMID 32171280, 2020). "A Phase 0/I trial on pancreatic cancer with FGFR1 amplification demonstrated that combined treatment with Nintedanib (200 mg/bid) and Letrozole resulted in a 55% average increase in plasma FGF23 levels, indicating effective FGFR1 inhibition." (PMID 39590377, 2024). "CAFs secrete FGF, which supports tumor growth and progression, and FGFR1–4 expression has been reported in pancreatic cancer, making them promising new therapeutic targets." (PMID 38672552, 2024). "Concomitantly, c-Myc S62 phosphorylation was increased upon FGF1-mediated FGFR1 activation leading to c-Myc stabilization and increase of c-Myc levels and pancreatic cancer cell growth." (PMID 39482742, 2024). "These preclinical findings underline the critical role of FGFR1 and FGFR2 in the pathophysiology of pancreatic cancer." (PMID 39199681, 2024). "In the FIGHT-101 clinical trial, one of five patients with pancreatic cancer showed a partial response to anti-FGFR1-3 treatment (pemigatinib); this case was positive for FGFR2::USP33 fusion." (PMID 38542259, 2024). "Further, we provide a comprehensive landscape of clinically actionable FGFR1-4 fusions across 30,229 pancreatic cancers." (PMID 39289482, 2024). "Genomic analysis of 30,229 comprehensively profiled pancreatic cancers revealed FGFR1-3 fusions in 245 cases, an incidence of 0.81%." (PMID 39289482, 2024). "The FGFR1/SRC/NF‐κB signaling axis plays a critical role in maintaining the stemness of pancreatic cancer cells." (PMID 37750089, 2023). "Mechanistic studies suggest that the presence of MUC4 mediates pancreatic cancer cell invasion and metastasis by stabilizing fibroblast growth factor receptor 1 and oncogenic signaling via interaction with HER3." (PMID 35255004, 2022). "Mechanistically, It has been confirmed that miR-15a-5p exerts its anti-pancreatic cancer activity by directly targeting FGFR1, which is highly expressed and executes cancer-promoting actions in PAAD." (PMID 35899199, 2022). "Resistance to trametinib (MEKs inhibitor) treatment via FGFR1-dependent activation of ERKs and AKT was also observed in lung and pancreatic cancer cells with mutated KRAS." (PMID 34830951, 2021). "In the present study, we demonstrate that KRAS‐mutant lung and pancreatic cancers are highly sensitive to concomitant inhibition of FGFR1 and PLK1." (PMID 34369083, 2021). "Consistently, FGFR1 overexpression was found significantly correlated with the better overall survival in pancreatic cancer patients." (PMID 34061869, 2021). "Next, the association between FGF19, FGF21, FGFR1, FGFR4, and KLB overexpression and the overall survival of pancreatic cancer patients was evaluated." (PMID 30593273, 2018). "According to The Cancer Genome Atlas (TCGA) study on pancreatic cancer, FGFR1 is upregulated in approximately 5% of pancreatic cancers." (PMID 30593273, 2018). "The main finding of this study is that FGFR1 protein expression defines clinically distinct subtypes of pancreatic cancer." (PMID 30593273, 2018). "In this study, we aimed investigate the clinical significance of FGFR1 expression in pancreatic cancer." (PMID 30593273, 2018).
pancreatic cancer (continued). "As FGFR1-positive pancreatic cancer has better prognosis, FGFR1 can be used as an independent predictor of better overall survival in pancreatic cancer patients." (PMID 30593273, 2018). "Then, to confirm the findings from the discovery cohorts, we performed immunohistochemistry (IHC) targeting FGFR1 protein in a validation cohort of 205 pancreatic cancer cases." (PMID 30593273, 2018). "Subsequently, to confirm the findings from the discovery cohorts, we performed immunohistochemistry (IHC) of FGFR1 protein in a validation cohort of 205 pancreatic cancer cases." (PMID 30593273, 2018). "Only a few previous studies have examined FGFR1 expression in pancreas cancers, and they reported a wide range of FGFR1 positivity (4–57%)." (PMID 30593273, 2018). "In this study, we aimed to investigate the clinical significance of FGFR1 overexpression in pancreatic cancer." (PMID 30593273, 2018). "Lehnen and colleagues reported that FGFR1 was expressed in 4% (5/125) of pancreatic cancer cases, and FGFR1 amplification was observed in 2.6% (4/155)." (PMID 30593273, 2018). "For example, over-expression of the IIIC isoform of FGFR1 in pancreatic cancer can promote tumourigenesis." (PMID 24503018, 2014). "As a consequence, over-expression of FGFR1-IIIc in pancreatic cancer promoted tumourigenesis, whereas over-expression of FGFR1-IIIb inhibited the malignant phenotype." (PMID 19920824, 2010). "Based on data that has attributed cellular functions to fibroblast proliferation in other tissues, we investigated a panel of ten central regulators of cell proliferation (c-Myc, Cyclin D1, Cyclin E1, FGF2, FGFR2, EGFR, EGF, FGF1, FGFR1 and VEGFA) in pancreatic cancer-associated fibroblasts (CAFs)." (PMID 38678032, 2024). "Indeed, in pancreatic cancer cells FGF1/FGFR1 signaling activates AKT pathway leading to GSK-3β phosphorylation and inhibition which finally results in decreased phosphorylation of c-Myc T58 and in reduced c-Myc proteasomal degradation." (PMID 39482742, 2024). "The presence of FGF/FGFR1–4 in pancreatic cancers may also be a useful therapeutic approach for PDAC." (PMID 38672552, 2024). "In addition to canonical RTK signalling, nuclear import of FGFR1 has been reported in a number of physiological contexts, including in breast and pancreatic cancers, where it can promote cancer cell invasion and therapy resistance." (PMID 36357571, 2023). "In sum, our analysis reveals that FGFR1 is a functional driver of EMT in pancreatic cancer." (PMID 35963908, 2022). "Indeed, exogenous FGF or FGFR1 inhibitors were able to modulate PD-L1 expression in pancreatic cancer cell lines." (PMID 34503236, 2021). "Finally, FGF1/2 bound to FGFR1 and induced PD-L1 mRNA and protein levels in pancreatic cancer cells." (PMID 34503236, 2021). "Our results of FGFR1 expression are in agreement with our recent study in which we established the clinical significance of FGFR1 through analysis of 313 pancreatic cancer patients along with the cross-validation done through Immunohistochemistry (IHC) of FGFR1 protein." (PMID 34061869, 2021). "A positive correlation was also found between FGFR1 and PD-L1 in pancreatic cancer tissues." (PMID 34503236, 2021). "Furthermore, multivariate analysis revealed FGFR1 positivity as an independent prognostic factor for better overall survival in pancreatic cancer patients (hazard ratio 0.677, 95% confidence interval 0.471–0.972, P = 0.035)." (PMID 30593273, 2018). "Our study is unique in that we evaluated FGFR1 expression based on the intensity of FGFR1 labeling, and we observed strong FGFR1 positivity in 15.7% (30 cases) and moderate/weak FGFR1 positivity in 61.8% (118 cases) in a cohort of Korean pancreatic cancer patients." (PMID 30593273, 2018). "In summary, FGFR1 overexpression, evaluated by IHC, may be used as a prognostic biomarker for overall survival in pancreatic cancer patients." (PMID 30593273, 2018).